DNMT3A (DNA methyltransferase 3 alpha)
Diseases named in the same sentence as DNMT3A in open-access papers (continued):
Sharing a sentence is not in itself a finding about the gene and the disease.
T-cell neoplasm (1 paper, 2020). "In addition to epigenetic modifiers implicated in all subtypes of T-cell neoplasm (TET2, DNMT3A, KMT2D, KMT2C, SETD2), recurrent mutations of the FAT1 tumor suppressor gene were for the first time recorded in 39% of cases." (PMID 31028364, 2020).
Tetralogy of Fallot (1 paper, 2023). A congenital cardiac malformation comprising pulmonary stenosis, overriding aorta, ventricular septum defect, and right ventricular hypertrophy. "Indeed, other studies have demonstrated correlations between DNMT3A and the tetralogy of Fallot and cardiac fibrosis." (PMID 36980848, 2023).
thymic lymphoma (1 paper, 2025). "Mice with heterozygous R878H DNMT3A mutations develop γ-radiation induced thymic lymphoma more rapidly than control mice, suggesting a vulnerability to stress stimuli in Dnmt3aR878H/+ cells." (PMID 40307617, 2025).
thymic neoplasm (1 paper, 2016). "To further address this issue, we analyzed DNA methylation levels of genes involved in one-carbon metabolism (MTHFR) and DNA methylation (DNMT1, DNMT3A, and DNMT3B) in blood, tumor tissue, and healthy thymic epithelial cells from MG patients that underwent a surgical resection of a thymic neoplasm." (PMID 27999265, 2016).
thyroid (1 paper, 2020). "All these findings suggest that DNMT3A alteration and the subsequent overall change in DNA methylation, plays an important role in thyroid pathogenesis as well, though the activating or inactivating nature of the alterations is still unknown." (PMID 33182397, 2020).
thyroid tumor (1 paper, 2020). A benign or malignant neoplasm affecting the thyroid gland. "Thyroid tumors show the second highest missense mutation rate (0.23; number of missense variants/number samples) affecting the DNMT3A PWWP domain amongst all cancers included in COSMIC, even higher than AML (0.13)." (PMID 33182397, 2020).
Uterine leiomyoma (1 paper, 2022). The presence of a leiomyoma of the uterus. "Chuang’s research manifested that the expression of miR-29c in uterine leiomyoma was inhibited, and its expression was negatively correlated with the expression of COL3A1 and DNMT3A." (PMID 35113040, 2022).
Varicose veins (1 paper, 2022). Enlarged and tortuous veins. "We found that both DNMT1 and DNMT3a were overexpressed in the endothelium of human varicose veins with blood reflux." (PMID 36293392, 2022). "DNMT1 and DNMT3a were overexpressed in the endothelium of human varicose veins with blood reflux (varicose vein F1)." (PMID 36293392, 2022).
vulvar squamous cell carcinoma (1 paper, 2020). An invasive squamous cell carcinoma arising from the vulva. "Some studies showed that overexpression of the DNMT3A protein in vulvar squamous cell carcinomas and pituitary adenomas is associated with malignant characteristics such as high invasiveness and recurrence." (PMID 32751889, 2020).
tumor (420 papers, 2004 to 2026). "In vivo studies using murine models have demonstrated a marked increase in the proportion of M2-polarized tumor-associated macrophages (TAMs) in the presence of DNMT3A mutations." (PMID 40861464, 2025). "The DNA methyltransferase gene DNMT3A is a tumor suppressor and epigenetic DNA-modifier associated with T-cell development." (PMID 40681778, 2025). "In a subset of AITLs, TET2 or DNMT3A have higher‐than‐expected VAF relative to other mutations or tumor content and are possible founder mutations present in hematopoietic stem/progenitor (HSPC) cells." (PMID 40510016, 2025). "In-depth profiling identified shared mutations in TET2 and DNMT3A (DNA methyltransferase 3 alpha) genes in both B and T cell tumours which suggested a common clonal origin, although molecular signatures later discerned two distinct malignancies." (PMID 40200078, 2025). "The DNMT3A rs227698 polymorphism exhibited an association with tumor response to treatment, which was assessed through the percentage of patients achieving complete or partial remission as per the Response Evaluation Criteria in Solid Tumors classification." (PMID 39597087, 2024). "Exome sequencing of the primary tumor identified an additional acquired, missense DNMT3A mutation in the dominant tumor clone, suggesting that the loss of DNMT3A function was relevant for the development of this tumor." (PMID 37160317, 2023). "Recently, a key role of Dnmt3a in the onset and progression of several types of cancers has been reported; in malignant tumor cells, Dnmt3a overexpression, mutations in the Dnmt3a gene, and an aberrant methylation pattern are observed." (PMID 36142137, 2022). "Truly, the expression of DNA methyltransferases DNMT1, DNMT3B and DNMT3A is often upregulated in different cancer cell lines and tissues, thereby causing the CpG islands hypermethylation of various tumor suppressor genes." (PMID 36366451, 2022). "While both TET2 and DNMT3A were tumor suppressive in MDS, this study showed that DNMT3A loss is the primary or causative genomic abnormality to disease progression and treatment resistance." (PMID 35563039, 2022). "We next used data generated by TCGA12 to investigate DNAm profiles in tumor samples from AML patients harboring either DNMT3A or TET2 driver mutations." (PMID 36097025, 2022). "Tumor growth suppression, reduced colony-forming capacity, and terminal differentiation in DNMT3A-mutated AML cells." (PMID 34012921, 2021). "A correlation between increased tumor risk or severity with the mutated DNA‐modifying enzymes DNMT3A and TET2 has been observed." (PMID 34754417, 2021). "Mutations in the gene encoding DNMT3a were reported in patients with various hematological malignancies, pointing to DNMT3a as a critically important new tumor suppressor." (PMID 34773997, 2021). "In PCs, DNMTs (especially DNMT3a and DNMT3b) were highly expressed, being associated with tumor progression." (PMID 34830196, 2021). "TET2/DNMT3A mutation status in 47,571 human tumor samples was analyzed at cBioPortal for Cancer Genomics." (PMID 34039392, 2021). "Functional studies showed that DNMT3A was essential for hematopoietic stem cell (HSC) differentiation and mutated DNMT3A initiated AML, suggesting DNMT3A acted as a tumor suppressor gene." (PMID 32597790, 2020). "DNMT3A mutations lead to localized hypermethylation affecting tumor-suppressor genes, including CDKN2B37; inhibited hematopoietic stem cell differentiation; and obstructed differentiation and leukemic transformation." (PMID 30635552, 2019). "Dnmt3a is frequently mutated in hematological tumors and has been defined as an important tumor suppressor." (PMID 30963999, 2019). "Although gene frequencies showed high concordance between tumor DNA and ctDNA, some differences persisted, such as the high mutation rate of DNMT3A in ctDNA." (PMID 30672098, 2019). "Recently, the relationship between the DNMT3A R882C mutation and the migration of tumor cells has been investigated in vitro." (PMID 30984620, 2019).
tumor (continued). "Multi-level and microdissected sampling strikingly reveal that many clones with different DNMT3A mutations exist in these benign tumors, suggesting that intra-tumor heterogeneity is common." (PMID 31624251, 2019). "Our results, together with accumulating evidence from other groups, demonstrates a clear relationship between the levels of Dnmt3a–Tet–5-hmC and tumorigenesis: the inactivation of this axis in adult stem cells predisposes them to tumor initiation." (PMID 28425913, 2017). "Deregulation of DNA methylation can alter gene expression, leading to tumor suppressor silencing or oncogene activation, and mutation/deregulation of Dnmt3a and Dnmt3b has been observed in several tumor types." (PMID 28425913, 2017). "Present data suggest that in contrast to hematologic malignancies where inactivating DNMT3A mutations reveal a tumor suppressor role, DNMT3A plays an oncogenic role as a key effector of VEGFA‐driven ovarian CSC expansion." (PMID 28179359, 2017). "To evaluate the role of Jdp2 in tumor maintenance we used an shRNA construct to knockdown the levels of Jdp2 in a Dnmt3a-deficient MYC-induced PTCL cell line." (PMID 27690235, 2016). "When DDX3 was depleted, loss of DDX3 increases DNMT3A accessibility to the promoter regions of these tumor-suppressive miRNAs and inhibit their expressions." (PMID 27344963, 2016). "While some of the mutations are oncogenic (i.e., IDH1/2, EZH2, and DNMT3A), others are tumor suppressive (i.e., KDM6A, CREBBP/EP300, and SMARCB1)." (PMID 27999365, 2016). "Altogether, our data demonstrate that changes in promoter methylation identified using WGBS likely represent tumor-specific events occurring in mouse PTCL driven by mono or bi-allelic loss of Dnmt3a." (PMID 27690235, 2016). "Given the lack of recurrent mutation hot spots within the ERG families in the tumor panel, DNMT3A was the only ERG that showed an OG-like alteration profile." (PMID 26110843, 2015). "Of note, the mutation in DNMT3A observed in tumor-infiltrating leukocytes and in the peripheral blood was present at 25-fold-higher mutant allele fraction in the tumor-infiltrating leukocytes compared with circulating leukocytes." (PMID 28721364, 2015). "As such, this system represents a unique model to investigate the cancer-associated methylation changes and to identify the epigenetic alterations that underpin the tumor-promoting effects of Dnmt3a mutations." (PMID 23284304, 2012). "The association of DNMT3A mutations with poor prognosis and the functional effects of DNMT3A mutations on human cells and mouse tumor models suggest that the loss of the enzymatic activity can drive tumorigenesis by inducing tumor-promoting epigenetic lesions." (PMID 23284304, 2012). "To confirm the presence of the tumor-inducing and -promoting genetic mutations, we analyzed the sequencing data for the K-ras and Dnmt3a loci." (PMID 23284304, 2012). "Taken together, these results highlight the potential of epigenetic alterations in DNMT1 and DNMT3a, as well as the DNA mutations in DNMT3b, as epigenetic and genetic factors to neoplastic diseases of chickens." (PMID 18648519, 2008). "TET2 or DNMT3A deficiency in HSPCs may favor a distinctive tumor milieu, but the functional effects of their loss in the TME of AITL needsx further exploration." (PMID 40510016, 2025). "Interestingly, increased DNMT3A expression in KIRC is linked to enhanced tumor suppression, suggesting a potential protective role." (PMID 40649942, 2025). "The genetic alterations in 12 PDX specimens suggest persistence of TET2 and DNMT3A loss during tumor passaging, but RHOAG17V showed more variations with disappearance in some PDX models and re‐emergence that follows TET2 loss in some after several passages, indicating more dynamic clonal selection." (PMID 40510016, 2025).
tumor (continued). "Notably, similar to other mutations affecting DNA methylation regulators such as NPM1, IDH2, and CEBPA, DNMT3A mutations have also been shown to upregulate tumor-specific antigens, which in turn can activate antigen-specific clonal T cell responses." (PMID 40861464, 2025). "Mutations in DNMT3A have also been found in tumor samples from several other hematological cancers." (PMID 39334883, 2024). "Furthermore, we detected changes associated with clonal hematopoiesis, including DNMT3A mutations, which were present in the majority of circulating tumour DNA samples." (PMID 37175518, 2023). "However, TET2 or DNMT3A mutations alone have been shown to be insufficient for tumor formation, and additional mutations are required to further drive the clonal expansion." (PMID 38199781, 2023). "The data on both polymorphisms and DNA methylation in the DNMT3A gene proved to be the most challenging and curious, suggesting that this gene could be further explored in inflammatory and tumor conditions." (PMID 37372315, 2023). "The acquired missense DNMT3A mutation in the dominant clone (which is also known to cause loss of function) suggests a strong selective pressure for near-total DNMT3A loss of function that probably represented the initiating event for this tumor." (PMID 37160317, 2023). "Other interesting candidates were NOX5, whose activation was demonstrated to inhibit cancer stem cell formation through ROS generation, and SALL3, which was reported to directly inhibit DNMT3A activity and consequently cause DNA hypomethylation and activation of tumor suppressor genes." (PMID 34439480, 2021). "Unlike what happens in patients with TBRS and in AML and other neoplasia, in which the gene is usually inactivated by loss-of-function alterations, we demonstrated that DNMT3A-mutated PGLs exhibited a significant overall methylation, indicating an activating role of the variants." (PMID 33182397, 2020). "In humans, DNA methyltransferases are involved in tumor transformation and progression resulting in genome-wide hypomethylation of tumor cells and silencing of tumor-suppressor genes; also, DNMT3A mutations have been associated with poor prognosis in acute myeloid leukemia." (PMID 30646578, 2019). "Moreover, transcriptional activation of EZH2 was associated with aberrant methylation of other tumor-related genes and DNMT3A upregulation in HNSCC." (PMID 30469511, 2018). "Using the Maxstat R function, that allow to determine the optimal cutpoint for continuous variables, we found that the maximum difference in OS and event-free survival (EFS) was obtained using a cut-off of 42% of DNMT3A-positive tumor cells that split patients in two groups (high and low risk)." (PMID 29721185, 2018). "We next wanted to characterize the molecular mechanisms that might underlie the tumor-suppressive function of Dnmt3a in the epidermis." (PMID 28425913, 2017). "Likewise, it has been proposed that gene body methylation is responsible of most of the transcriptional changes underlying the ability of Dnmt3a to promote neural SCs differentiation, and in protecting the lung epithelium from tumor progression." (PMID 28425913, 2017). "Whereas HOT genes represent good candidates to explain the tumor suppressor function of Dnmt3a, demonstration of a causative oncogenic role in initiation/progression of lymphomagenesis for any of these genes is challenging as it requires long-term in vivo experiments in mice." (PMID 27690235, 2016). "In addition, both myeloid deficiencies and neoplasms were observed in mice transplanted with Dnmt3a-null bone marrow obtained from Mx1-Cre;Dnmt3afl/fl mice, altogether highlighting the importance of Dnmt3a in prevention of myeloid transformation." (PMID 27690235, 2016).
tumor (continued). "The current study suggested that at least some DNMT3A polymorphisms, including the DNMT3A promoter SNP, may play different roles in the development and progression of these two tumor types." (PMID 20128888, 2010). "Second, both loss-of-function study of DNMT3A by siRNA-mediated knockdown and gain-of-function study of miR-143 by enforced miR-143 expression produced a suppressive effect on tumour cell growth, suggesting that their effects on cellular transformation are inversely correlated." (PMID 19638978, 2009). "Our results suggested that the aberrant methylation profiles of DNMT1 and DNMT3a as well as CpG to TpG transitions in DNMT3b are complex epigenetic and genetic factors that may be involved with neoplastic disease susceptibility or resistance in chickens." (PMID 18648519, 2008). "Thus it is possible that the tissue-specific epimutations of DNMT3a is associated with the tumor number variations in different tissues." (PMID 18648519, 2008). "For example, the detection rate of ctDNA DNMT3A mutations was dramatically higher than in tumor DNA (8.33% vs 2.86%), a phenomenon that could be attributed to clonal hematopoiesis, which intrinsically leads to substantial noncancerous mutations in blood circulation." (PMID 30672098, 2019). "DNMT3A mutations may also play an important role in tumor metastasis." (PMID 28127428, 2017). "Interest in studying the role of Dnmt3a in normal hematopoiesis was fueled by findings that in a number of hematologic malignancies of myeloid and T-cell origin Dnmt3a was mutated primarily in the catalytic domain, suggesting that methyltransferase activity is critical to prevent tumor development." (PMID 27563627, 2016). "In conclusion, our studies confirmed that DNMT3a acted as a tumour promoter to induce malignant progression of LUAD by upregulating HDAC7 and further inducing the upregulation of ZEB1 and c-Myc." (PMID 39990668, 2025). "Then, the role of DNMT3a in promoting tumour metastasis was confirmed in a nude mouse lung metastasis model." (PMID 39990668, 2025). "Overall, mutated genes identified in the tumor‐enriched cohort were concordant, with recurrent variants identified in TET2, DNMT3A, RHOA, IDH2, and TET3." (PMID 40510016, 2025). "The impact of tumor environment was evaluated in the same patient population against the expression of DNMT3A and GMPS." (PMID 41465346, 2025). "For example, the miR-29 family can target DNA methyltransferases DNMT3A/3B, downregulating their expression, thereby relieving the methylation silencing of tumor suppressor genes, such as p15 and RASSF1A." (PMID 41394878, 2025). "Alternatively, and in accordance with previous studies, TET2, DNMT3A, and TET3 were sometimes observed in the myeloid or B‐cell fraction in addition to the tumor indicating it was likely an early founding mutation that occurred in a progenitor cells." (PMID 40510016, 2025). "In Case 1, the mutation profiles of the two tumor lesions shared only a PDGFRA and DNMT3A missense mutation and a CHEK2 frameshift mutation." (PMID 40589631, 2025). "In contrast, in KIRP, higher DNMT3A expression promotes tumor cell proliferation by silencing tumor suppressor genes, accelerating KIRP progression." (PMID 40649942, 2025). "RNA expression of tumor-specific antigens in primary AML samples is associated with mutations in epigenetic modifiers, such as DNMT3A." (PMID 39078434, 2025). "These CHIP-related mutations, particularly in genes such as DNMT3A, TET2, and ASXL1, can be inadvertently detected in plasma cfDNA and misattributed to the tumor, resulting in false-positive findings and erroneous clinical interpretations." (PMID 40869308, 2025). "In vivo, HDAC7 overexpression was verified to significantly increase the weight of subcutaneous tumours in the A549 DNMT3a knockdown group, as demonstrated by xenograft assays in nude mice." (PMID 39990668, 2025).